FAIM2 (Fas apoptotic inhibitory molecule 2)
Description:
Antiapoptotic protein which protects cells uniquely from Fas-induced apoptosis. Regulates Fas-mediated apoptosis in neurons by interfering with caspase-8 activation. May play a role in cerebellar development by affecting cerebellar size, internal granular layer (IGL) thickness, and Purkinje cell (PC) development.
Synonyms: KIAA0950; LFG; LFG2; NMP35; TMBIM2; LIFEGUARD; NGP35
Tractability: Antibody: UniProt places it where antibodies can reach, with medium confidence; UniProt predicts a signal peptide or a membrane-spanning region; its Gene Ontology location is reachable by antibodies, with medium confidence.
Gene: Protein-coding gene on chromosome 12 (49,866,896 to 49,904,217, reverse strand). Ensembl gene ENSG00000135472.
Subcellular location: Cell membrane; Membrane raft; Postsynaptic cell membrane
Subcellular location (Human Protein Atlas): Intermediate filaments
Gene Ontology:
Molecular function: protein binding; calcium channel activity
Biological process: negative regulation of extrinsic apoptotic signaling pathway via death domain receptors; regulation of neuron apoptotic process; cerebellar granular layer development; cerebellar Purkinje cell differentiation; cerebellar Purkinje cell layer development; cerebellum development; negative regulation of apoptotic process; negative regulation of neuron apoptotic process; calcium ion transmembrane transport
Cellular component: Golgi membrane; membrane raft; endoplasmic reticulum membrane; Golgi apparatus; endoplasmic reticulum; membrane; plasma membrane; postsynaptic membrane
Genetic constraint (gnomAD): Loss-of-function variants: 27 observed, 49.47 expected, observed/expected ratio (o/e) 0.55, 90% interval 0.4 to 0.75. The upper end of that interval is the gene's LOEUF score, 0.75, which puts it in group 3 of 6, group 1 being the genes least tolerant of losing a copy. Missense variants: 311 observed, 403.15 expected, observed/expected ratio (o/e) 0.77, 90% interval 0.7 to 0.85. Synonymous variants: 156 observed, 165.05 expected, observed/expected ratio (o/e) 0.95, 90% interval 0.83 to 1.08.
Homologues: Orthologues: chimpanzee FAIM2 (99% identical), pig FAIM2 (96% identical), macaque FAIM2 (94% identical), rabbit FAIM2 (94% identical), guinea pig FAIM2 (93% identical), rat Faim2 (93% identical), mouse Faim2 (92% identical), dog FAIM2 (92% identical), tropical clawed frog faim2 (68% identical), zebrafish faim2b (48% identical), Drosophila melanogaster Lfg (31% identical), Drosophila melanogaster Nmda1 (31% identical), and 5 more. Paralogues in human: TMBIM1 (48% identical), GRINA (41% identical), TMBIM4 (25% identical), GHITM (17% identical), TMBIM6 (14% identical).
Diseases named in the same sentence as FAIM2 in open-access papers:
FAIM2 is named in the same sentence as 72 diseases in open-access papers, as found by Europe PMC text mining. Sharing a sentence is not in itself a finding about the gene and the disease. The quoted sentences say what the papers report.
Obesity (30 papers, 2009 to 2025). Accumulation of substantial excess body fat. "Other genes containing SNP variants associated with obesity and related traits in children and adolescents are the Fas apoptotic inhibitory molecule 2 (FAIM2) and neurexin 3 (NRXN3)." (PMID 41082226, 2025). "At the FAIM2 locus on chr 12q13.12, we observed known genes associated with obesity, eating patterns, and diabetes-related traits, including ASIC1, AQP2, AQP5, AQP6, RACGAP1, and AC025154.2 (AQP5-AS1) along with FAIM2." (PMID 39813287, 2025). "In this sense, other variants of FAIM2 in the 3′UTR region are associated with obesity and body adiposity in other GWAS." (PMID 39337639, 2024). "FAIM2 is linked to obesity and dyslipidemia in the Chinese population, while GNAI3 is associated with non-alcoholic fatty liver disease (NAFLD)." (PMID 37620670, 2023). "The role of FAIM2 in obesity has already been documented which is a prime risk factor in PDAC development." (PMID 36329447, 2022). "A previous large-scale GWA study identified FAIM2 (rs7138803) as being associated with obesity in Caucasian adults." (PMID 32228543, 2020). "In this case, rs1108923 is selected in the dataset because it maps to the upstream region of the obesity gene FAIM2, but the tool considers this variant to be within the region of ASIC1." (PMID 29163640, 2017). "In this study on high cardiovascular risk subjects (48% patients with type 2 diabetes) from a Mediterranean population, we found, as in other studies, that the variant allele of the FAIM2-rs7138803 polymorphism was associated with higher obesity risk." (PMID 24393375, 2014). "Although a polymorphism (rs7138803; G > A) near the Fas apoptotic inhibitory molecule 2 (FAIM2) locus has been related to obesity, its association with other cardiovascular risk factors and disease remains uncertain." (PMID 24393375, 2014). "Our meta-analyses have shown the important role of 2 polymorphisms (SH2B1 rs7498665 and FAIM2 rs7138803) in the development of overweight/obesity." (PMID 24621099, 2014). "Increased risk of overweight/obesity was also observed in FAIM2 rs7138803 polymorphism (overall OR = 1.11, 95% CI = 1.01-1.22, P = 0.04)." (PMID 24621099, 2014). "Although it is known that the FAIM2 gene codifies an evolutionary conserved inhibitor of Fas-mediated apoptosis and the apoptotic pathways are higher in obesity, the mechanisms by which this association occurs are not known." (PMID 24393375, 2014). "The FAIM2 (Fas apoptotic inhibitory molecule 2) is one of the less well-known genes associated with obesity." (PMID 24393375, 2014). "Our results identified significant associations between 2 polymorphisms (SH2B1 rs7498665 and FAIM2 rs7138803) and overweight/obesity." (PMID 24621099, 2014). "Our meta-analysis among 3477 cases and 4676 controls demonstrated that FAIM2 rs7138803 was associated with the risk of overweight/obesity (overall OR = 1.11, 95% CI = 1.01-1.22, P = 0.04)." (PMID 24621099, 2014). "Increased risk of overweight/obesity was also observed in rs7138803 of FAIM2 among 3,477 cases and 4,676 controls from five studies (overall OR = 1.11, 95% CI = 1.01-1.22, P = 0.04)." (PMID 24621099, 2014). "This study highlighted the importance of above two candidate genes (SH2B1 and FAIM2) in the risk of overweight/obesity." (PMID 24621099, 2014). "Large scale GWAS identified an association between common variant rs7138803, between BCDIN3D, FAIM2 gene of 12q13 and obesity in over 30,000 adult individuals of European Caucasians." (PMID 23924573, 2013). "Hypothalamus Aif1 is also linked to Lta and Faim2, genes that regulate apoptosis and also reported as associated with obesity." (PMID 19463160, 2009). "There is evidence that FAIM2 expression may increase susceptibility to type 2 diabetes associated with obesity and to obstructive sleep apnea-related cardiac injury, thus, the FAIM2 downregulation (found in TRA subjects) appears to bear favorable effects." (PMID 33546468, 2021).
Obesity (continued). "Recent publications confirmed that FAIM2 may be a susceptibility gene for fat accumulation and obesity." (PMID 29258237, 2017). "Mutations of FAIM2 which interferes with Fas-mediated cell death confer risk for obesity." (PMID 24621099, 2014). "FAIM2 rs7138803 polymorphism is associated with increased risk of obesity in Japanese." (PMID 24621099, 2014). "Therefore, polymorphisms in FAIM2 (rs7138803) are speculated to induce obesity by enhancing appetite and suppressing adipocyte apoptosis, which are consistent with the current study showing an association of risk allele and increased BMI." (PMID 32228543, 2020). "The study was trying to expand the association of the FAIM2 SNP rs7138803 with obesity previously identified in multiple cohorts of European descents to a Chinese Han population, and to further provide the evidence of obesity susceptibility of the FAIM2 locus to multiple obesity-related traits." (PMID 23924573, 2013). "In summary, the obtained results suggest that regions 8q22-24, 11q23-25, and 12q13-15 are very likely to contain genes like VPS13B, APOA5, ZPR1, BUD13, and FAIM2 that control obesity-related factors in Iranian families with MetS21,22,27,28,31,32." (PMID 33727680, 2021). "Several obesity susceptibility loci in genes, including GNPDA2, SH2B1, TMEM18, MTCH2, CDKAL1, FAIM2, and MC4R, have been identified by genome-wide association studies." (PMID 32228543, 2020). "It is known that the obesity gene, the apoptotic suppressing molecule Fas 2 (FAIM2), is regulated by nutritional status, and the promoter FAIM2 methylation levels are significantly related to overweight." (PMID 33193078, 2020). "Studies about FAIM mainly focused on the neural and reproductive organ development, only few reports showed that the FAIM2, another member of FAIM family, was associated with obesity and dyslipidaemia." (PMID 31270932, 2019). "Recently the association between the Fas apoptotic inhibitory molecule 2 (FAIM2)-rs7138803 polymorphism and greater obesity risk has been replicated." (PMID 25928419, 2015). "After adjusting for age, sex and admixture, significant associations with obesity were found for 6 genes in the case-control study (ADIPOQ, FTO, TMEM18, INSIG2, FAIM2/BCDIN3 and BDNF)." (PMID 23950976, 2013). "Novel functions of three other genes, FAIM2, MAP2K5, and TFAP2B, were also found to be associated with obesity development." (PMID 22355368, 2012). "Considering the pathological role of fat accumulation, a biological process FAIM2 may participate in, therefore, obesity may demonstrate specific functional relationships with the pathogenesis of myocardial infraction." (PMID 29258237, 2017). "In addition, 7 of the 17 (41.2%) GWAs-selected genes (FTO, TMEM18, INSIG2, FAIM2/BCDIN3, BDNF, SH2B1 and MC4R) were associated with obesity in this population." (PMID 23950976, 2013). "Thus, FAIM2 promoter methylation levels could be influenced by sedentary behavior and physical activity affecting health status in children with obesity." (PMID 35813370, 2022). "Taken together, among seven common obesity risk loci, the loci near TMEM18 (rs6548238), CDKAL1 (rs7754840), and FAIM2 (rs7138803) are associated with obesity, and loci near TMEM18 (rs6548238) and FAIM2 (rs7138803) are susceptibility loci for obese type 2 diabetes." (PMID 32228543, 2020). "We found that loci near TMEM18 (rs6548238), CDKAL1 (rs7754840), and FAIM2 (rs7138803) may be associated with obesity-related indicators, and loci near TMEM18 (rs6548238) and FAIM2 (rs7138803) may increase susceptibility of concurrent type 2 diabetes associated with obesity." (PMID 32228543, 2020).
lung carcinoma (11 papers, 2016 to 2024). "ARGs play important roles in the progression of several tumors, especially in the process of metastasis: FAIM2 overexpression is associated with adverse clinical outcome in lung cancer, L1CAM affects the prognosis of endometrial cancer (EC)." (PMID 37664042, 2023). "For example, the anoikis-associated genes KLF5 and FAIM2 are associated with the prognosis of colorectal and lung cancer, respectively, and silencing KLF5 and FAIM2 can significantly inhibit cancer cell anoikis resistance and proliferation." (PMID 36996495, 2023). "She and his colleagues revealed that overexpression of FAIM2 is associated with dismal clinical outcome for lung cancer, and silencing FAIM2 may inhibit tumor cell viability and anoikis resistance." (PMID 34992654, 2021). "To further validate our observations from the CCLE database, we performed quantitative real-time PCR (qRT-PCR) for FAIM2 expression in 12 lung cancer cell lines." (PMID 27677402, 2016). "According to the study, FAIM2 overexpression in lung cancer leads to adverse clinical outcomes, while silencing FAIM2 may decrease tumor cell viability and resistance to anoikis." (PMID 39391236, 2024). "SNHG7 overexpression has been found in lung cancer, and SNHG7 could promote lung cancer cells proliferation, invasion, and inhibit apoptosis by enhancing the FAIM2 expression." (PMID 29047230, 2017). "In addition, a recent study showed that SNHG7 overexpression promotes cell migration and invasion in lung cancer by enhancing the FAIM2 expression." (PMID 29047230, 2017). "LncRNA-SNHG7 promotes the proliferation of lung cancer cells by enhancing the FAIM2 expression." (PMID 28388563, 2017). "In lung cancer, the upregulation of lncRNA-SNHG7 was reported to accelerate the proliferation, migration, and invasion of lung cancer cells by upregulating FAIM2 expression." (PMID 34568020, 2021). "In lung cancer, SNHG7 stimulates proliferation, migration, and invasion while inhibiting apoptosis through up-regulation of FAIM2 (Fas apoptotic inhibitory molecule 2) and miR-193b sponging." (PMID 32318335, 2020). "In several cancers, including colorectal cancer, prostate cancer, esophageal cancer, lung cancer and gastric cancer, lncRNA SNHG7 has been known as a potent oncogene by targeting GALNT1, Cyclin D1, FAIM2, p15 and p16." (PMID 30853913, 2019).
diabetes (5 papers, 2020 to 2025). "This is further supported by the fact that many of the closely correlating protein-coding genes have themselves been previously implicated in diabetes, such as FAIM2, JAZF1, and XBP1, as well as others whose connections likely remain uncharacterized." (PMID 37218990, 2023). "After adjusting for age and sex, the loci near TMEM18 (rs6548238) and FAIM2 (rs7138803) were significantly associated with diabetes." (PMID 32228543, 2020). "Likewise, other SNPs of the FAIM2 gene could produce increased BMI and thus, a high risk of diabetes." (PMID 39337639, 2024). "Cumulatively, under expression of both FAIM2 and NPY have shown strong negative correlation between diabetes and hyper-methylation of both genes which are significant co-morbidity factors in the Indian patient population." (PMID 36329447, 2022).
small cell lung carcinoma (5 papers, 2016 to 2025). Small cell lung cancer (SCLC) is a highly aggressive malignant neoplasm, accounting for 10-15% of lung cancer cases, characterized byrapid growth, and early metastasis. "FAIM2 was described as a therapeutic target in small cell lung cancer and as a predictive marker of poor outcome in breast cancer patients." (PMID 34503120, 2021). "Knock-down of FAIM2 can significantly affect tumor cell proliferation in small-cell lung cancer." (PMID 32328342, 2020).
breast carcinoma (4 papers, 2021 to 2022). "Of note, FAIM2 has been previously linked to TRIM21 in a breast cancer study." (PMID 35468884, 2022). "In breast cancer cells, production of apoptotic molecule 2 (FAIM2) through downstream of TrkB counteracts apoptosis induced by cisplatin." (PMID 34395067, 2021). "Sub-cluster 18 and 20 displayed a high expression of FAIM2, an inhibitory protein in the Fas-apoptotic pathway of tumor cells, which was proposed as a tumor marker in small cell lung and breast cancer." (PMID 34503120, 2021).
non-small cell lung carcinoma (4 papers, 2016 to 2023). A group of at least three distinct histological types of lung cancer, including non-small cell squamous cell carcinoma, adenocarcinoma, and large cell carcinoma. "As a member of ARGs, the expression of Fas apoptotic inhibitory molecule 2 (FAIM2) was positively linked to tumor stage and poor endpoint of non-small cell lung cancer, and FAIM2 knockdown may inhibit anoikis resistance." (PMID 37056778, 2023). "FAIM2 may promote bone metastasis through the Wnt signaling pathway in patients with non-small-cell lung cancer." (PMID 35693786, 2022). "In this study, we show that FAIM2, an inhibitory molecule in the Fas-apoptosis pathway, is significantly overexpressed in SCLC compared to non-small cell lung cancer." (PMID 27677402, 2016).
type 2 diabetes (4 papers, 2011 to 2021). "After adjusting for age and sex, CT or CC genotypes at the locus near TMEM18 (rs6548238) and AA or AG genotypes of the FAIM2 (rs7138803) locus were associated with type 2 diabetes." (PMID 32228543, 2020). "Univariate logistic regression analysis showed that the loci near TMEM18 (rs6548238) and FAIM2 (rs7138803) were associated with type 2 diabetes." (PMID 32228543, 2020). "Our study found that AA or AG genotypes of FAIM2 (rs7138803) were most frequent in overweight/obese patients with type 2 diabetes in a Chinese Han population." (PMID 32228543, 2020). "The risk of type 2 diabetes has only been addressed in two other studies, and here association between TMEM18, GNPDA2, ETV5, FAIM2 and SH2B1 and a BMI-dependent increased risk of type 2 diabetes have been reported." (PMID 21912638, 2011). "After adjusting for sex and age, loci near TMEM18 (rs6548238) and FAIM2 (rs7138803), but not SH2B1 (rs7498665), near GNPDA2 (rs10938397), MTCH2 (rs10838738) and near MC4R (rs12970134), were associated with increased risk for type 2 diabetes in obese individuals." (PMID 32228543, 2020).
glioma (3 papers, 2020 to 2022). A benign or malignant brain and spinal cord tumor that arises from glial cells (astrocytes, oligodendrocytes, ependymal cells). "Western blotting showed that the expression level of FAIM2 was down-regulated in glioma (including LGG and GBM) tissues." (PMID 36185230, 2022). "The results of the current study showed that FAIM2 is closely related to the regulation of immunity and play an anti-tumor role in glioma (GBM and LGG)." (PMID 36185230, 2022). "All these results demonstrated that FAIM2 overexpression can inhibit the proliferation of glioma cells." (PMID 36185230, 2022). "To detect the effect of FAIM2 in glioma, we constructed stable FAIM2 glioma cell lines including U87 and U251." (PMID 36185230, 2022). "In glioma, the co-expression gene of FAIM2 were shown in a volcano plot and the top 50 genes positively and negatively correlated with FAIM2 were displayed in the heat map." (PMID 36185230, 2022). "Next, we explored FAIM2 co-expression genes in Glioma using the LinkedOmics database to verify the potential function of FAIM2 in glioma." (PMID 36185230, 2022). "Here, we conducted a pan-cancer analysis to explore the role of FAIM2 in various tumors and further verified the results in glioma through molecular biology experiment." (PMID 36185230, 2022). "Furthermore, we explored the role of FAIM2 in intracellular signaling regulation and regulatory factor activity and verified the tumor suppressor effect of FAIM2 in glioma by molecular biology experiments." (PMID 36185230, 2022). "Furthermore, we conducted molecular biology experiments in glioma further verified the tumor suppressor role of FAIM2." (PMID 36185230, 2022). "IHC and Western blotting confirmed that FAIM2 expression was downregulated in glioma tissues." (PMID 36185230, 2022). "Next, we validated the role of FAIM2 in Glioma by molecular biological methods." (PMID 36185230, 2022). "Glioma and control normal brain tissues were used to identify the expression level of FAIM2." (PMID 36185230, 2022). "Molecular biology experiments verified a cancer suppressor role for FAIM2 in glioma." (PMID 36185230, 2022). "All these results indicated that FAIM2 might play an essential role in regulating the immune response of the TME in glioma." (PMID 36185230, 2022). "FAIM2 may serve as a potential pan-cancer biomarker for prognosis and immune infiltration, especially in glioma." (PMID 36185230, 2022). "We compared the expression levels of FAIM2, DLGAP2, ATP1B1 and RALYL using ONCOMINE databases and found that these 4 genes were significantly downregulated in brain and CNS cancer compared with the normal group." (PMID 33323543, 2020).
colorectal cancer (2 papers, 2019 to 2022). A primary or metastatic malignant neoplasm that affects the colon or rectum. "Moreover, SNHG7 and FAIM2 are upregulated in colorectal cancer tissues compared with normal adjacent tissues." (PMID 35747807, 2022).